KRAS (KRas proto-oncogene, GTPase)
Diseases named in the same sentence as KRAS in open-access papers (continued):
Sharing a sentence is not in itself a finding about the gene and the disease.
pancreatic adenocarcinoma (continued). "Furthermore, obesity related immunological processes have been linked to KRAS induced cancer initiation of pancreatic adenocarcinoma in mice." (PMID 25415225, 2015). "KRAS mutations are present in 90% of pancreatic adenocarcinomas." (PMID 29546098, 2015). "KRAS mutations are common in ampullary cancer although the 25 to 37% incidence appears to be lower than the approximately 95% rate of KRAS mutation seen in pancreatic adenocarcinomas." (PMID 22762308, 2012). "Notably, KRAS exhibits the highest frequency of mutations in Pancreatic Adenocarcinoma (PAAD), followed by Colon Adenocarcinoma (COAD) and Lung Adenocarcinoma (LUAD), which are also tumor types that garner considerable attention from the cancer research community." (PMID 39455841, 2024). "Antigenic drift poses a particular challenge when targeting neoantigens such as EGFRvIII in glioblastoma or KRAS G12D in pancreatic adenocarcinoma." (PMID 41262250, 2025). "KRAS mutations represent one of the most common oncogenic drivers in LUAD, pancreatic adenocarcinoma, and other malignancies, yet therapeutic options directly targeting KRAS remain limited and prone to resistance." (PMID 40936169, 2025). "The therapeutic efficacy of adagrasib and sodagrasib has been reported for patients with KRAS p.Gly12Cys mutant pancreatic adenocarcinoma." (PMID 38542259, 2024). "Here, we describe that this combination strategy facilitates the anti-tumoral activity of KRAS G12D inhibition and successfully breaks down therapeutic resistance in pancreatic adenocarcinoma." (PMID 39687047, 2024). "In summary, we have demonstrated that MRTX1133 sensitivity shows high variability in KRAS G12D mutant pancreatic adenocarcinoma models in 2D culture." (PMID 39687047, 2024). "Our study warrants further investigation for the potential applicability of KRAS G12D inhibitors in combination with farnesyl-transferase inhibitors for the treatment of KRAS mutant pancreatic adenocarcinoma." (PMID 39687047, 2024). "Of note, we also found B7-H3–high pancreatic adenocarcinomas to display fewer inactivating mutations in RNF43, which has recently been shown to accelerate the progression of KRAS-driven pancreatic neoplasia." (PMID 38709075, 2024). "In vivo evaluations of RMC-6236 resulted in significant and durable tumor regression across multiple tumor types, particularly in NSCLC and pancreatic adenocarcinomas harboring KRAS glycine-12 substitutions (KRAS G12X)." (PMID 39337530, 2024). "Three KRAS G12D mutant human pancreatic adenocarcinoma cell lines were tested in conventional 2D cultures for sensitivity to MRTX1133, a specific non-covalent inhibitor of the KRAS G12D protein." (PMID 39687047, 2024). "Our findings warrant further investigation of the applicability of KRAS G12D targeting in combination with farnesyl-transferase inhibitors in KRAS G12D mutant pancreatic adenocarcinoma." (PMID 39687047, 2024). "The KRAS gene has high value in the diagnosis, prognosis, and possible future therapeutic regimens in patients with pancreatic adenocarcinoma." (PMID 35454771, 2022). "Due to momelotinib’s ability to target TBK1, it was studied in KRAS-mutated NSCLC in combination with the MEK 1/2 inhibitor trametinib and in pancreatic adenocarcinoma in combination with nab-paclitaxel and gemcitabine chemotherapy." (PMID 34773474, 2022). "For this purpose, we used The Cancer Genome Atlas (TCGA) database of pancreatic adenocarcinoma patients with low and high expression of polymerase theta carrying KRAS wild-type or oncogenic KRASG12D to generate a survival curve." (PMID 36077614, 2022). "To validate these results at the endogenous level, we repeated the experiment in the KRAS-mutant pancreatic adenocarcinoma cell line CFPAC-1, except we immunoblotted for endogenous KRAS protein." (PMID 34504076, 2021).
pancreatic adenocarcinoma (continued). "It has been demonstrated that oncogenic KRAS mediates the reprogramming of glutamine metabolism in pancreatic adenocarcinoma cells by modifying the transcription of metabolic enzymes in a noncanonical pathway of glutamine." (PMID 33777798, 2021). "In PBMCs from pancreatic adenocarcinoma patients, the platform enriched neoplastic cells identified by their KRAS mutant status using droplet digital PCR with one hour of processing." (PMID 34561533, 2021). "In sum, loss of EFR3A (and/or EFR3B) expression inhibits oncogenic signaling in human KRAS-mutant pancreatic adenocarcinoma cells, which manifests as a reduction in transformed and tumorigenic growth." (PMID 34504076, 2021). "In contrast, there was no significant change in cellular morphology or N-cadherin levels in TGFβ-treated Panc02.13 cells, a KRAS wt pancreatic adenocarcinoma cell line, although a slight decrease in the levels of E-cadherin was observed." (PMID 34944824, 2021). "Of note, neither TCR conferred cytotoxic activity against HLA matched BxPC-3 tumor cells, a KRAS WT pancreatic adenocarcinoma cell line, validating the specificity of each TCR for the cognate G12V peptide." (PMID 34272369, 2021). "To independently validate these results, we repeated the experiment in the KRAS-mutant human pancreatic adenocarcinoma cell lines PANC-1, AsPC-1, and CFPAC-147." (PMID 34504076, 2021). "Given this, we next assayed the effect of C7 on endogenous oncogenic KRAS signaling in KRAS-mutant human pancreatic adenocarcinoma cell lines." (PMID 34504076, 2021). "In the early 1990s, two independent studies noted the presence of specific KRAS proto‐oncogene GTPase (KRAS) and NRAS proto‐oncogene GTPase (NRAS) mutations in cfDNA from pancreatic adenocarcinoma and patients with acute myelogenous leukemia." (PMID 33969622, 2021). "Over 95% of pancreatic adenocarcinomas (PDACs), as well as a large fraction of other tumor types, such as colorectal adenocarcinoma, are driven by KRAS activation." (PMID 31413817, 2019). "KRAS plays roles in both the initiation and maintenance of pancreatic adenocarcinoma by altering metabolic pathways such as increasing glucose uptake and autophagy." (PMID 30759745, 2019). "In a subset of lung and pancreatic adenocarcinomas addicted to mutant KRAS, the disruption of galectin-3/β3 interaction by GCS-100, a galectin-3 antagonist currently under clinical development, released mutant KRAS from β3 and inhibited tumor growth in mice." (PMID 31109009, 2019). "In conclusion, our results indicate that disrupting LIF signaling, which directly fuels oncogenic KRAS-driven pancreatic adenocarcinoma, has an impact on tumorigenicity of KRAS and overcomes the characteristic resistance to chemotherapy." (PMID 31296870, 2019).
pancreatic adenocarcinoma (continued). "KRAS-mutant tumors, including lung and pancreatic adenocarcinomas, require active NF-κB signaling and NF-κB inhibition blocks KRAS-induced tumor growth." (PMID 29445180, 2018). "Our work highlights that like NSCLCs, KRAS mutant pancreatic adenocarcinomas cannot be regarded as a homogeneous group." (PMID 28957417, 2017). "We bioinformatically identify low expression of various autophagy genes in pancreatic adenocarcinoma and correlate it with oncogenic KRAS status and poor prognosis." (PMID 28581519, 2017). "Here, we analyzed how mutation and natural selection contribute to differences in the distribution of KRAS driver substitutions between lung, colon and pancreatic adenocarcinomas." (PMID 26902163, 2016). "This strategy may offer a novel therapeutic avenue for targeting KRAS-driven tumors, particularly pancreatic adenocarcinoma." (PMID 41322195, 2025). "The absence of KRAS mutation in a pancreatic adenocarcinoma served as a critical clue suggesting metastatic disease rather than a primary pancreatic malignancy." (PMID 40656425, 2025). "The absence of characteristic mutations, such as KRAS, in a presumed pancreatic adenocarcinoma should prompt consideration of metastatic disease and trigger additional molecular and immunohistochemical studies." (PMID 40656425, 2025). "The absence of KRAS mutation in a pancreatic adenocarcinoma should prompt consideration of metastatic disease, particularly from the lung." (PMID 40656425, 2025). "Interestingly, we observed higher wild-type KRAS in this cohort than historical data which showed around 10% wild-type KRAS in pancreatic adenocarcinoma." (PMID 39456541, 2024). "Finally, combination of additional KRAS G1C and farnesyl-transferase inhibitors also shows synergism in lung, colorectal and pancreatic adenocarcinoma cellular models." (PMID 38278976, 2024). "Here, we have demonstrated that the application of tipifarnib, one of the most potent farnesyl-transferase inhibitors results in synergistic anticancer effects in combination with KRAS G12D targeting pancreatic adenocarcinoma cells that have been shown to be therapy-resistant under 2D conditions." (PMID 39687047, 2024). "Interestingly, PHF13 depletion significantly downregulated the targets of KRAS (3G), which is frequently activated in most pancreatic adenocarcinomas and is known to be an essential driver of human cancer." (PMID 35597793, 2022). "Based on these results, we performed viability assays with six pancreatic adenocarcinoma human cell lines (PDAC) harbouring different oncogenic KRAS mutations and with a non-transformed cell line, all of them epithelial." (PMID 36138080, 2022). "KRAS G12A has been identified in lung, colon, colorectal and rectal adenocarcinoma, and uterine endometrioid carcinoma, while KRAS Q61K has been found in colon, colorectal and pancreatic adenocarcinoma." (PMID 34525976, 2021). "EFR3A gene amplification also tracked with KRAS-mutant pancreatic adenocarcinoma samples." (PMID 34504076, 2021). "To evaluate the role of endogenous EFR3A in a cancer driven by an oncogenic mutation in the native KRAS gene, we targeted EFR3A, EFR3B, or both genes by CRISPR/Cas9-mediated gene inactivation as above in the KRAS-mutant human pancreatic adenocarcinoma cell line HPAF-II47." (PMID 34504076, 2021). "Although a limited number of samples, differentiating KRAS mutation-positive (n = 64) from KRAS mutation-negative (n = 115) pancreatic adenocarcinoma samples revealed higher EFR3A expression in the former." (PMID 34504076, 2021).
pancreatic adenocarcinoma (continued). "Notably, two recent studies have shown that autophagy inhibition synergizes with pharmacological targeting of the KRAS downstream effectors MEK1/2 or ERK, preventing growth of KRAS-driven pancreatic adenocarcinomas." (PMID 31544066, 2019). "Moreover, analysis of the Pancreatic Adenocarcinoma study in TCGA datasets reveals that among 178 samples with genomic sequencing and mRNA expression data, 151 (85%) have alterations in KRas." (PMID 30214681, 2018). "Furthermore, the vast majority (90–95%) of pancreatic adenocarcinomas harbor mutant forms of the KRAS oncogene." (PMID 29930346, 2018). "By comparing the expression of mCherry reporters we were able to reveal in vivo signaling pathways elicited after oncogenic KRAS constitutive activation in both pancreas and cerebellum, showing in vivo how TGFβ, Notch and Shh are involved in pancreatic adenocarcinoma and during MDB carcinogenesis." (PMID 24878567, 2014). "Unlike most pancreatic adenocarcinoma cell lines, BxPC-3 has wild-type KRas, while S2-013 carries the common KRasG12D mutation." (PMID 23991074, 2013). "Additionally, several cancers with poor prognostic outcomes, such as pancreatic adenocarcinoma, are driven by other non-G12C KRAS mutations and thus have no effective targeted therapies." (PMID 41309533, 2025). "However, molecular analysis revealed the absence of KRAS mutation in the pancreatic lesion, which is highly unusual for primary pancreatic adenocarcinoma." (PMID 40656425, 2025). "However, then, simtuzumab, a function-blocking antibody against LOXL2 with an antidesmoplastic effect in vitro, did not improve the clinical results in patients with KRAS-mutated colorectal or pancreatic adenocarcinoma." (PMID 33379400, 2020). "There is considerable overlap between the effector pathways of SEMA3C and KRAS; both lead to PI3K/AKT and Raf/MEK/ERK activation and SEMA3C expression positively correlates with KRAS mutations in The Cancer Genome Atlas (TCGA) datasets of pancreatic adenocarcinoma." (PMID 30759745, 2019). "Of 1,791 patients with pancreatic adenocarcinoma, 36 (2.0%) had an ERBB2 amplification, 26 (72.2%) of whom had a KRAS alteration." (PMID 38406801, 2024). "When wild type KRAS is found in a pancreatic adenocarcinoma, there is always some alternative gene, usually a growth factor receptor or RAS family gene that replaces KRAS as the leading cancer instrument." (PMID 38607041, 2024). "Alterations in KRAS, which plays a role in the Ras/Raf/MEK/ERK pathway, were observed in pancreatic adenocarcinoma." (PMID 38672586, 2024). "Considering that KRAS mutation might occur as an early event in pancreatic adenocarcinoma, the present study began with KRAS mutation grouping, which was followed by the construction of prognostic models based on WGCNA to predict the prognosis of PAAD." (PMID 34134622, 2021). "In KRAS-dependent tumors such as pancreatic adenocarcinomas (PDAC), KRAS inhibition has demonstrated to increase autophagic signaling resulting in autophagy dependance." (PMID 31355143, 2019).
pancreatic adenocarcinoma (continued). "For example, pancreatic adenocarcinoma was shown to have a strong YAP component, as KRAS-induced acinar-to-ductal metaplasia depends on YAP expression for progression to malignant ductal adenocarcinoma." (PMID 27935819, 2017). "Dual luciferase reporter assays confirmed that KRAS and ANXA2 can bind miR-206 directly at the “seed site”, which is consistent with previous reports showing that miR-206 targets KRAS and ANXA2 in pancreatic adenocarcinoma." (PMID 27191262, 2016). "Conversely, most adenocarcinomas, such as colon (COAD, blue) and pancreatic adenocarcinomas (PAAD, black) had a low prevalence of KRAS A146 mutations and were not responsive to LZTR1 knockout in DepMap." (PMID 41542462, 2026). "Consistent with our data, analyzes of pancreatic adenocarcinoma in The Cancer Genome Atlas (TCGA) and Australian Pancreatic Genome Initiative (APGI) revealed that copy number variations of the KRAS gene were only attributed to amplification, with a low incidence." (PMID 39779977, 2025). "For example, KRAS essentiality was markedly stronger in KRAS-mutant stomach adenocarcinoma (STAD), rectal adenocarcinoma (READ), pancreatic adenocarcinoma (PAAD) and colon adenocarcinoma (COAD) lineages, whereas BRAF essentiality was strongest in BRAF-mutant skin cutaneous melanoma (SKCM)." (PMID 39009815, 2024). "Pancreatic adenocarcinoma (67.5%) was the most prevalent digestive adenocarcinoma without APC alteration but with KRAS alteration." (PMID 38672586, 2024). "In all cancer patients with KRAS mutations, we found gastrointestinal (GI) tract cancers: esophageal carcinoma (ESCA), stomach adenocarcinoma (STAD), colon adenocarcinoma (COAD), rectum adenocarcinoma (READ) and pancreatic adenocarcinoma (PAAD), had the lowest K20 prediction scores." (PMID 37141389, 2023). "Furthermore, FOSL1 genetic inhibition was found to be detrimental to KRAS-driven cancers such as LUAD and pancreatic adenocarcinoma." (PMID 36612054, 2022). "A novel finding of this study was the upregulation of 9-cis RA upon TGFβ treatment in pancreatic adenocarcinoma cells that harbor a mutant KRAS gene, while these changes were not apparent in Panc02.13 cells." (PMID 34944824, 2021). "Furthermore, we mined sequencing data for 126 pancreatic adenocarcinoma patient-derived xenograft (PDX) models and identified an additional KRAS wild-type tumour with a PDZRN3-RAF1 fusion, which conserves the RAF1 kinase domain." (PMID 31097696, 2019). "Similarly, cell lines with KRAS G12C had a significant lower mean LN(IC50) in the cancer-type-specific setting, encompassing LIHC, LUAD, LUSC, and pancreatic adenocarcinoma (PAAD)." (PMID 30053901, 2018). "Interestingly, decreased REDD1 expression, a stress response gene which is associated with peroxisome proliferator activated receptor γ (PPARγ)/CD36 activation, predicts poor outcomes selectively in KRAS mutant but not KRAS wild-type human lung and pancreatic adenocarcinomas." (PMID 36675307, 2023). "The rates of digestive adenocarcinoma without APC, KRAS, and CDKN2A alterations in patients with biliary tract, gastric, colorectal, and pancreatic adenocarcinomas were 54.8%, 21.0%, 18.5%, and 5.6%, respectively." (PMID 38672586, 2024). "Interestingly, components of EFR3A signaling are upregulated in human pancreatic adenocarcinoma, but not other tested RAS-mutant (KRAS, NRAS, or HRAS) cancers." (PMID 34504076, 2021).